PADI2 (peptidyl arginine deiminase 2)
Description:
Catalyzes the deimination of arginine residues of proteins.
Synonyms: KIAA0994; PAD2; PDI2; PAD-H19
Tractability: Small molecule: a structure with a bound ligand is known; a high-quality ligand is known. Antibody: its Gene Ontology location is reachable by antibodies, with high confidence. PROTAC: its protein half-life has been measured; a small molecule that binds it is known.
Target class: Enzyme; Hydrolase
Chemical probes: ML325
Gene: Protein-coding gene on chromosome 1 (17,066,761 to 17,119,459, reverse strand). Ensembl gene ENSG00000117115.
Subcellular location: Cytoplasm
Pathways (Reactome):
Chromatin organization: Chromatin modifying enzymes
Immune System: Neutrophil degranulation
Gene Ontology:
Molecular function: histone H3R26 arginine deiminase activity; nuclear estrogen receptor binding; protein homodimerization activity; protein-arginine deiminase activity; histone arginine deiminase activity; calcium ion binding
Biological process: estrogen receptor signaling pathway; negative regulation of chemokine-mediated signaling pathway; negative regulation of lymphocyte chemotaxis; substantia nigra development; transcription initiation-coupled chromatin remodeling; chromatin remodeling
Cellular component: cytoplasm; euchromatin; extracellular exosome; azurophil granule lumen; cytosol; extracellular region; nucleus
Genetic constraint (gnomAD): Loss-of-function variants: 51 observed, 48.6 expected, observed/expected ratio (o/e) 1.05, 90% interval 0.84 to 1.33. The upper end of that interval is the gene's LOEUF score, 1.33, which puts it in group 5 of 6, group 1 being the genes least tolerant of losing a copy. Missense variants: 712 observed, 724.92 expected, observed/expected ratio (o/e) 0.98, 90% interval 0.92 to 1.04. Synonymous variants: 279 observed, 298.19 expected, observed/expected ratio (o/e) 0.94, 90% interval 0.85 to 1.03.
Homologues: Orthologues: chimpanzee PADI2 (100% identical), macaque PADI2 (99% identical), dog PADI2 (95% identical), pig PADI2 (94% identical), rat Padi2 (94% identical), mouse Padi2 (93% identical), guinea pig PADI2 (92% identical), rabbit PADI2 (91% identical), tropical clawed frog padi2 (61% identical), zebrafish padi2 (53% identical). Paralogues in human: PADI1 (52% identical), PADI3 (51% identical), PADI4 (50% identical), PADI6 (45% identical).
Diseases named in the same sentence as PADI2 in open-access papers:
PADI2 is named in the same sentence as 121 diseases in open-access papers, as found by Europe PMC text mining. Sharing a sentence is not in itself a finding about the gene and the disease. The quoted sentences say what the papers report.
breast carcinoma (39 papers, 2010 to 2025). "Peptidyl arginine deiminase 2 (PADI2) is overexpressed in breast cancer and is associated with tumorigenesis and progression." (PMID 35216622, 2022). "It has also been reported that PADI2 is a breast cancer susceptibility gene, whose expression promotes tumor development through ACSL4, BINC3 and CA9 signaling pathways." (PMID 32951601, 2020). "All these observations clearly highlight the functional association of PADI2 in breast cancer pathogenesis." (PMID 32079300, 2020). "Both Sequenom MassARRAY and TaqMan genotyping assays demonstrated that SNP rs10788656 in the PADI2 gene was significantly associated with breast cancer." (PMID 27478411, 2016). "The two genotyping methods with two independent cohorts provided the first evidence that the PADI2 gene confers susceptibility to breast cancer." (PMID 27478411, 2016). "In addition to its role in inflammation and in breast cancers, PADI2 is also implicated in other cancer types, including skin cancer." (PMID 32079300, 2020). "The present study demonstrated that PADI2 significantly increases susceptibility to breast cancer." (PMID 27478411, 2016). "We therefore focused on investigating the pathogenic mechanism of PADI2 in breast cancer." (PMID 27478411, 2016). "Feline mammary carcinomas had complete loss of nuclear PADI2 expression." (PMID 27478411, 2016). "On the other hand, for UNB, specific upregulated DEGs included SMIM3, a leukemia promoter gene, WNT7A, a hypoxia induced EMT driver, PADI2, a tumorigenic breast cancer gene, and RAPGEF4, which modulates gliomas." (PMID 38538643, 2024). "It has been reported that the overexpression of PADI2 can increase tamoxifen resistance in breast cancer cells." (PMID 37020554, 2023). "In breast cancer cells, PADI2 citrullinates the C-terminal domain (CTD) of RNApolII, which acts as a regulatory hub where PTMs mediate the binding of auxiliary factors, determining polymerase progression." (PMID 35706669, 2022). "PADI2 inhibits proliferation of colon cancer cells and can be used as a potential marker for breast cancer." (PMID 34131588, 2021). "Several studies have shown that PADI2 enhances carcinogenesis in a variety of cancers, including breast cancer, spontaneous skin tumors, epithelial bladder cancer, and colon cancer." (PMID 32951601, 2020). "Among PADI family members, PADI2 is highly expressed in primary breast tumors and luminal breast cancer cell lines." (PMID 32079300, 2020). "Meta-analysis from large cohorts of breast cancer patients and related healthy individuals showed that among PADI gene family members, only PADI2 is overexpressed in breast cancer and other cancers, as its overexpression correlates with poor prognosis." (PMID 32079300, 2020). "PADI2 regulates transcription in human mammary epithelial cells, promotes epithelial-to-mesenchymal transition in mammary tumor cells, and facilitates ductal invasion in primary mouse mammary organoids." (PMID 32079300, 2020). "Peptidyl arginine deiminase 2 (PADI2) was first reported as an important biomarker for HER2/ERBB2+ breast cancers." (PMID 29050308, 2017). "PCR array analyses, including cancer pathway finder and signal transduction PCR arrays, were performed to investigate the tumorigenic pathway of PADI2 in the MCF-7 breast cancer cell line following treatment with anti-PADI2 siRNA." (PMID 27478411, 2016). "The current study detected decreased expression of BIRC3 in breast cancer cells when PADI2 expression was suppressed using anti-PADI2 siRNA." (PMID 27478411, 2016). "It is possible that the increased expression of PADI2 in breast cancer cells up-regulates BIRC3 expression through ER and NF-κB to simulate anti-apoptotic functions." (PMID 27478411, 2016). "We show by RNA-seq that PADI2 mRNA expression is highly correlated with HER2/ERBB2 (p = 2.2 × 106) in luminal breast cancer cell lines." (PMID 23110523, 2012).
breast carcinoma (continued). "The observation that PADI2 is upregulated in the luminal subtype confirms previous gene expression data where PADI2 was identified as one of the top upregulated genes in luminal breast cancer lines compared to basal lines." (PMID 23110523, 2012). "In humans, PADI2 is one of the most upregulated genes in luminal breast cancer cell lines compared to basal lines." (PMID 23110523, 2012). "RNA-seq data from a collection of 57 breast cancer cell lines was queried for PADI2 levels, and correlations with known subtype and HER2/ERBB2 status were evaluated." (PMID 23110523, 2012). "For the study, we first documented PADI2 expression and activity during mammary tumor progression, and then investigated the effects of PADI inhibition in cell cultures, tumor spheroids, and preclinical in vivo models of breast cancer." (PMID 23110523, 2012). "In breast cancer, PADI2 can mediate cell migration by promoting the EGF signaling pathway." (PMID 37020554, 2023). "This may be because PADI2 can affect gene expression through epigenetic modifications in breast cancer." (PMID 37020554, 2023). "For example, PADI2 and PADI4 can catalyze the guanylation of histones H3 and H4 at the gene promoter, leading to local alterations in chromatin structure and regulation of tumor-associated gene transcription in human breast cancer cells." (PMID 36471887, 2022). "Our previous study has shown that PADI1 can regulate to function on MEK1 via citrullination and therefore affect MEK1 enzyme activity in breast cancer cells, therefore, we wondered whether PADI2 could play the similar role." (PMID 33747724, 2021). "PAD4 has previously been shown to be elevated in lung adenocarcinoma, to play roles in A549 EMT transition and to be important for PAD4-mediated NETosis in lung epithelial malignancies, while PADI2 has been related to prostate cancer proliferation and is elevated in breast cancer." (PMID 32629995, 2020). "On the other hand, PADI2 can specificity citrullinates histone H3 arginine 26 citrullination (H3Cit26) that leads to chromatin decondensation and transcriptional activation in human breast cancer cells." (PMID 32079300, 2020). "Here, we review the recently discovered functions of PADI2-mediated citrullination of the C-terminal domain of RNA polymerase II in transcriptional regulation in breast cancer cells and the proposed mechanisms to reshape the transcription regulatory network that promotes cancer progression." (PMID 32079300, 2020). "They furthermore found that PADI2 mRNA expression is highly correlated with HER2 (human epidermal growth factor receptor-2), a well-known diagnostic maker for breast cancer, in a luminal breast cancer cell line." (PMID 27478411, 2016). "To strengthen the hypothesis that PADI2 is primarily expressed in luminal breast cancer cell lines and is coexpressed with HER2/ERBB2, we next investigated PADI2 mRNA levels by querying RNA-seq datasets collected from 57 breast cancer cell lines." (PMID 23110523, 2012). "In summary, we provide here an important new line of evidence demonstrating that PADI2 may play a role in the oncogenic progression of cancer and, in particular, breast cancer." (PMID 23110523, 2012). "Given the previous correlations between PADI2 and the HER2/ERBB2 oncogene, the goal of this study was to carry out an initial test of the hypothesis that PADI2 plays a role in breast cancer progression." (PMID 23110523, 2012). "Subsequent studies are now underway to test whether PADI2 plays a functional role in HER2/ERBB2 driven breast cancers, potentially by functioning as an inflammatory mediator." (PMID 23110523, 2012). "Furthermore, we show that, across a wide array of breast cancer cell lines, PADI2 is specifically overexpressed in the luminal subtype, while also being highly correlated with HER2/ERBB2 overexpression." (PMID 23110523, 2012). "Given these previous studies, our goal was to formally test the hypothesis that PADI2 plays a role in mammary tumor progression." (PMID 23110523, 2012).
breast carcinoma (continued). "Indeed, it is known that some of the inflammatory stimuli that lead to PADI4 activation in neutrophils, such as chemotactic peptides, incite a calcium influx and a similar mechanism has been attributed to progesterone-dependent PADI2 activation in breast cancer cells." (PMID 35706669, 2022). "In addition, PADI2-mediated citrullination of histone H3 Arg26 (H3R26) has also been shown to promote the transcriptional activation of estrogen receptor α (ERα) target genes in breast cancer and of interleukin 6 (IL-6) in multiple myeloma." (PMID 35706669, 2022). "Moreover, several recent studies have suggested that PADI2 is involved in tumorigenesis and plays an important role in the progression of skin neoplasia, myeloma, breast cancer, and CRC, although its tumorigenic effect and mechanism are largely unknown." (PMID 29050308, 2017). "However, PADI2 expression was reduced in mammary carcinomas from both species." (PMID 27478411, 2016). "Thus, the goals of this study were to examine whether PADI2 plays a role in mammary tumor progression, and whether the inhibition of PADI activity has anti-tumor effects." (PMID 23110523, 2012). "In breast cancer, PAD2 has a major role in cell proliferation, and PADI2 is over-expressed in luminal subtype cells." (PMID 38132149, 2023). "Recent studies have suggested that PADI2 (PAD isoform 2), a member of the PAD family, is involved in the tumorigenic process of some tumors, especially breast cancer." (PMID 27478411, 2016). "EGF up-regulates PADI2 transcription and translation in CMT25 cells, a canine mammary tumor cell line." (PMID 27478411, 2016). "Lastly, we document that PADI2 expression is highly correlated with HER2/ERBB2 overexpressing and luminal subtype breast cancers." (PMID 23110523, 2012). "We also investigated the level of PADI2 mRNA in MMTV-Wnt-1 mice, which is a basal mouse model of breast cancer." (PMID 23110523, 2012). "In this study, we show that PADI2 is specifically upregulated during mammary tumor progression and that the PADI inhibitor, Cl-amidine, is effective in inhibiting the growth of PADI2 overexpressing cell lines in both 2D and 3D cultures." (PMID 23110523, 2012). "PADI2 regulates RNA polymerase II (RNAP2) transcriptional activity by catalyzing the deamination of R1810 to Cit1810, thus promoting gene transcription and cell proliferation in breast cancer." (PMID 35216622, 2022). "We found that the absence of PADI2-mediated cit1810 of RNAP2 reduced cell proliferation of breast cancer cells, by modulating cell cycle progression." (PMID 32079300, 2020). "Taken together, these findings indicate that PADI2 is predominantly expressed in luminal epithelial cells, and that there appears to be a strong relationship between PADI2 and HER2/ERBB2 expression in breast cancer." (PMID 23110523, 2012). "Together, these results suggest that PADI2 may function as an important new biomarker for HER2/ERBB2+ tumors and that Cl-amidine represents a new candidate for breast cancer therapy." (PMID 23110523, 2012). "To test whether PADI2 expression is elevated in HER2/ERBB2 expressing cells in vivo, we next measured PADI2 mRNA in normal murine mammary epithelium and in primary mammary tumors collected from MMTV-neu mice." (PMID 23110523, 2012). "PADI2 can also citrullinate R1810 (cit1810) at RNAP2-CTD (RNA polymerase II), promote the interaction with the P-TEFb (positive transcription elongation factor b) complex, lead to the release of RNAP2, and promote the transcription of cell cycle genes and the proliferation of breast cancer cells." (PMID 37020554, 2023).
rheumatoid arthritis (28 papers, 2012 to 2025). A chronic, systemic autoimmune disorder characterized by inflammation in the synovial membranes and articular surfaces. "PADI2 encodes an enzyme involved in protein citrullination, a clinically targeted pathway implicated in a range of diseases such as atherosclerosis, rheumatoid arthritis, lupus, and multiple sclerosis." (PMID 29710874, 2018). "Variants unique to a specific autoimmune disease such as those in PADI2 and PADI4 that are associated with rheumatoid arthritis are also discussed, addressing their role in disease-specific immunopathology." (PMID 35979360, 2022). "It was previously shown that PADI2 is expressed at high levels in neutrophils and macrophages to accumulate within the joint rapidly, so it is particularly relevant in the pathogenesis of rheumatoid arthritis (RA)." (PMID 37627159, 2023). "Of the five PADI isoforms, PADI2 and PADI4 are the most studied, and the excessive citrullination of target proteins by their abnormal enzyme activity is one of the main causes of some diseases, such as rheumatoid arthritis (RA) and many cancer types." (PMID 35218410, 2022). "We aimed to identify the relationship between polymorphisms in PADI2 and PADI4 in developing interstitial lung disease in patients with rheumatoid arthritis, their correlation with the PAD2, PAD4 protein levels, and clinical characteristics in RA-ILD." (PMID 37759458, 2023). "A total of 320 SNPs from the PADI locus (including PADI1, PADI2, PADI3, PADI4 and PADI6 genes) were genotyped in 1,238 RA cases and 1,571 control subjects from the Malaysian Epidemiological Investigation of Rheumatoid Arthritis (MyEIRA) case-control study." (PMID 23164236, 2012).
Sepsis (21 papers, 2019 to 2025). Sepsis is defined as life-threatening organ dysfunction caused by a dysregulated host response to infection. "Deletion of Padi2 enhances survival and diminishes lung injury in sepsis, while Padi4 deficiency benefits the LPS-induced endotoxic shock model but not in cecal ligation and puncture (CLP) or pneumonia models." (PMID 39405117, 2024). "Concurrently, C10 IMs also increased after sepsis (0.4% in WT Sham versus 39.1% in WT PA), with a subsequent decreased level observed following Padi2 and Padi4 deficiency (39.1% in WT PA versus 18.7% in DKO PA)." (PMID 39405117, 2024). "In sepsis and sepsis-induced acute lung injury, the selective inhibition of PADI2 using small-molecule inhibitors increased the survival rate of sepsis model mice." (PMID 41146353, 2025). "Intriguingly, the deletion of Padi2 and Padi4 modulated this myeloid-macrophage differentiation and polarization, consequently altering the inflammatory milieu within the lung after sepsis." (PMID 39405117, 2024). "Our research aimed to elucidate how Padi2 and Padi4 deletions affect these mechanisms, revealing that such deletions enhance survival rates and mitigate lung injury in a PA pneumonia–induced sepsis mouse model." (PMID 39405117, 2024). "Padi2 and Padi4 deletion led to an increase in mature AMs after PA infection, potentially improving bacterial clearance and reducing sepsis-induced ALI." (PMID 39405117, 2024). "It was noted that several genes with DRE were previously reported or implicated to play a role in sepsis or SAE, such as superoxide dismutase 2 (SOD2), Miat, peptidylarginine deiminase 2 (Padi2), Shank1, transcription factor 4 (Tcf4) and kinesin family member 3 (Kif3c)." (PMID 39135964, 2024). "Padi2 and Padi4 deficiency reduces ALI in a PA pneumonia–induced sepsis mouse model." (PMID 39405117, 2024). "Moreover, in sepsis, PADI2 can promote Caspase-11-dependent pyroptosis and reduce the antibacterial activity of macrophages, thereby exacerbating sepsis." (PMID 37020554, 2023). "Our study shows that Padi2–/– Padi4–/– double KO (DKO) improved survival, reduced lung injury, and decreased bacterial load in Pseudomonas aeruginosa (PA) pneumonia–induced sepsis mice." (PMID 39405117, 2024). "Among the 5 related calcium-dependent PADI isoforms, PADI2 and PADI4 are highly expressed in monocytes and macrophages, and they play substantial roles in the immune response to sepsis." (PMID 39405117, 2024). "This study investigated the roles of PADI2 and PADI4 enzymes in regulating the immune response during sepsis, particularly focusing on their influence on the critical balance between proinflammatory and antiinflammatory pathways." (PMID 39405117, 2024). "Higher concentrations of PADI2 have been detected in serum and BALF of patients with sepsis and septic mice." (PMID 39405117, 2024). "While research has predominantly focused on the individual deletion of Padi2 or Padi4, the combined effect of Padi2 and Padi4 double KO (DKO; Padi2–/– Padi4–/–) on sepsis and its progression, particularly in the context of lung injury, is not well understood." (PMID 39405117, 2024). "Peptidyl arginine deiminase 2 (PADI2) and PADI4 play crucial roles in mediating the host’s immune response in sepsis, but their specific functions remain unclear." (PMID 39405117, 2024). "Considering the potential critical roles of both PADI2 and PADI4 in sepsis, we hypothesize that the deletion of both Padi2 and Padi4 could offer a marked therapeutic advantage." (PMID 39405117, 2024).